CCND1 (cyclin D1)
Diseases named in the same sentence as CCND1 in open-access papers (continued):
Sharing a sentence is not in itself a finding about the gene and the disease.
liver cancer (continued). "Previous studies showed that miR-520b could inhibit growth or proliferation of liver cancer cells by target oncogenes, such as CCND1." (PMID 32214367, 2020). "Besides, Cyclin D1 modulates liver cancer stem cells self-renewal, interacting with and activating Smad2/3 and Smad4." (PMID 33317149, 2020). "Similarly, overexpressed E2F7 could significantly impact AKT/β‐catenin/CCND1 signaling pathway and promote the liver cancer stem cells to self‐renew and cell cycle entry." (PMID 35924788, 2022). "In conclusion, EZH2 c.1544A>G and CCND1 c.839A>T might be potential biomarkers of liver cancer." (PMID 34604069, 2021). "Overall, EZH2 c.1544A>G and CCND1 c.839A>T might be novel potential biomarkers of liver cancer." (PMID 34604069, 2021). "MEKK2 and cyclin D1 may serve as therapeutic targets of liver cancer." (PMID 22319632, 2012). "In liver cancer stem cells, HULC was shown to induce autophagy via the miR-675/PKM2 pathway, leading to upregulation of Cyclin D1 and promoting the proliferation of liver cancer stem cells." (PMID 40909946, 2025). "Prior report revealed that Sor treatment suppressed the G1 phase protein cyclin D1 expression in HCC, while PGV-1 itself has been shown to promote mitotic arrest in liver cancer cells HepG2 and JHH-7." (PMID 39628938, 2024). "Suppression of cyclin D1 and the PI3K/AKT pathway by isoliquiritigenin exhibits antitumor properties in Hep3B cells, a liver cancer cell line." (PMID 36985568, 2023). "We plan to explore how PI3K, AKT, CDK1, CCND1 and RAF1 contribute to arecoline-induced liver cancer using a rat intrahepatic tumor transplantation model and siRNA interference." (PMID 35836300, 2022). "To further investigate the influence of CACHD1 in regulation of the cell cycle, we analyzed mRNA expression of cyclin D1 and p21WAF1/Cip1 genes in CACHD1 knockdown human liver cancer cell lines." (PMID 33802238, 2021). "First, according to the western blot experiment, the expression of Cyclin D1, MMP2, and MMP9 decreased significantly, indicating that the overexpression of miR-141 can inhibit the proliferation, migration, and invasion of liver cancer cells." (PMID 34675977, 2021). "Focal amplification on 5p15.33 (TERT) and 11q13.3 (CCND1, FGF19) was found in 7 (38.1%) and 3 (9.52%) liver cancer patients, respectively." (PMID 32458568, 2020). "During hepatic carcinogenesis, Cyclin D1 is induced by activated β-catenin, it can partially substitute activated β-catenin and cooperates with the oncogene MET to induce liver cancer formation in vivo." (PMID 33317149, 2020). "Obtained results disclosed that Lanatoside C inhibits Wnt/β-catenin signaling, along with Cyclin D1 and c-MYC expression in breast, lung, and liver cancers." (PMID 31783627, 2019). "Cellular functional analysis demonstrated that miRNA-302a/d negatively regulates self-renewal capability and cell cycle entry of liver cancer stem cells via suppression of its target gene E2F7 and its downstream AKT/β-catenin/CCND1 signaling pathway." (PMID 30326936, 2018). "This suggests that in the pathogenesis of liver cancer, TM4SF1 upregulates cyclin D1 and PCNA and thereby promotes the growth, proliferation, and invasion of cancer cells." (PMID 27153056, 2016). "SHP appears to suppress tumorigenesis in liver cancer, inhibiting tumor growth and increasing sensitivity to apoptotic stimuli, due to repression of LRH-1-dependent Cyclin D1 transcription." (PMID 26421305, 2015). "CCND1, a key cell cycle regulator, is commonly overexpressed or amplified in various cancers including HCC, and its silencing has been shown to suppress liver cancer stem cell differentiation." (PMID 41321947, 2025). "Within liver cancer (SMMC-7721) cells, ginsenoside Rg3 potentiates oxaliplatin's anti-cancer properties, curbing liver cancer growth and facilitating cell death through the control of PCNA and Cyclin D1 expression." (PMID 40490812, 2025).
liver cancer (continued). "Additionally, miR-217 reduced liver cancer cell proliferation and halted G1/S transition by targeting EZH2, Cyclin-D1, MTDH, and KLF5." (PMID 39273339, 2024). "A knockout of HNF4α increases chemically induced liver cancer in rodents and P1-HNF4α interacts with cyclin D1 in a negative reciprocal regulatory axis to control hepatocyte proliferation." (PMID 37600688, 2023). "miRNA-302a/d could downregulate the self-renewal ability of liver cancer stem cells and proliferation of liver cancer cells by inhibiting E2F7/AKT/β-catenin/CCND1 signaling pathway." (PMID 36360311, 2022). "Furthermore, the suppression of cyclin D1 (CD1) mRNA expression was demonstrated by RT-PCR analysis in both CACHD1kn-2 Huh7 and HepG2 liver cancer cell lines." (PMID 33802238, 2021). "Specific to the luminal A comparison was the gene CCND1 (oncogene; breast and pan-cancer), the second most interconnected after ESR1 (oncogene; breast and pan-cancer), while ELOVL6 (oncogene; liver cancer) was the most interconnected unique gene within the luminal B vs TNBC network." (PMID 32605588, 2020). "Interestingly, previous in vitro investigation reported a cell cycle arrest in the G1 phase in liver cancer cells treated with ponatinib, and identified that this cell cycle blockade was mediated by a reduction in the function of the CDK4/CDK6/Cyclin D1 complex." (PMID 32719607, 2020). "During induction of liver cancer using the MRHM, the proliferation of hepatocytes increases; therefore, we tested whether 4.5 mT - 120 Hz ELF-EMF exposure affects the expression of PCNA, Ki-67 and cyclin D1." (PMID 20416104, 2010). "Significantly, various known YAP/TEAD1 targeted genes, such as BIRC5, AREG, CCND1, CTGF, and MYC, were not activated through SRGN-mediated YAP signaling in liver cancer cell lines." (PMID 40384866, 2025).
osteosarcoma (105 papers, 2006 to 2026). A usually aggressive malignant bone-forming mesenchymal neoplasm, predominantly affecting adolescents and young adults. "Additional predicted targets of miR-30a and miR-30e within this pathway include PIK3CA, mTOR, FOXO3, MMP13, SOX9, BCL2, VEGFA, and CCND1, all of which have been previously associated with osteosarcoma pathogenesis." (PMID 40862758, 2025). "A previous study reported the ability of curcumin to down-regulate ERRα expression in osteosarcoma cells (OS) causing a reduction in cyclin D1 expression and tumor growth." (PMID 36831394, 2023). "In osteosarcoma studies, silencing of gli2 is found to cause upregulation of p21, inhibition of cyclin D1, SKP2, and phosphorylated Rb, thus inducing G1 phase arrest and ultimately preventing the growth of osteosarcoma." (PMID 37868974, 2023). "Cell cycle experiments and Western blot analysis showed that most osteosarcoma cells overexpressing hsa_circ_0087302 were arrested in G0/G1 phase, and hsa_circ_0087302 overexpression affected the expression of cyclin D1, a cycle-associated protein." (PMID 36035366, 2022). "We also found that decreased osteosarcoma cell proliferation induced by KDM5A deficiency was associated with downregulation of cyclin D1 and upregulation of p27, P21, and apoptosis regulator Bax." (PMID 33436536, 2021). "In summary, our data showed that naringin inhibits the malignant phenotype of osteosarcoma cells by inhibiting the expression of Zeb1 and Zeb1-associated proteins such as Cyclin D1 and MMP2." (PMID 30580326, 2018). "However, in osteosarcoma cells, G1 cell cycle arrest was observed, and the expression of cyclin D1 and cyclin A2 was decreased due to Cdc6 deficiency." (PMID 33020506, 2020). "Silent CPE expression can suppress cyclin D1 expression, leading to cell cycle arrest and inhibiting the proliferation and metastasis of osteosarcoma cells." (PMID 41001032, 2025). "cyclin-D1 elevation in control groups can be attributed to HIF-1α which activated the AKT/Cyclin-D1 pathway stimulate the tumor development in osteosarcoma cells." (PMID 40205002, 2025). "A previous study showed that CARM1 promotes tumorigenesis via the pGSK3β/β-Catenin/cyclin D1 signaling pathway in osteosarcoma." (PMID 38476024, 2024). "Coincidentally, miR-195 has been identified as a potential therapeutic target in osteosarcoma treatment due to its ability to inhibit CCND1, thereby exhibiting tumor metastasis suppressor properties." (PMID 38190139, 2024). "For example, LncRNA LINC01296 promoted cell proliferation and metastasis of osteosarcoma through regulating cell cycle protein cyclin D1." (PMID 36807122, 2023). "Our observations showed that the suppression of NTN1 not only reduced the proliferation and migration of osteosarcoma, chondrosarcoma, and antler cartilage cells but also downregulated the expression of oncogenic cyclin D1 in these cells." (PMID 37446017, 2023). "In osteosarcoma, the C-myc/Cyclin D1 pathway often contributes to osteosarcoma progression by altering the cell cycle, DNA repair, and cell migration." (PMID 38031136, 2023). "A study investigating if inhibiting the Notch pathway prevents osteosarcoma growth demonstrated that a γ-secretase inhibitor attenuated the cyclin D1, cyclin E1, E2, and SKP2 expression." (PMID 36012128, 2022). "In conclusion, lnc-KASRT serves as a potential treatment target by regulating SRSF1-related KLF6 alternative splicing and the P21/CCND1 pathway in osteosarcoma." (PMID 34568030, 2021).
osteosarcoma (continued). "Lnc-KASRT serves as a potential treatment target via regulating SRSF1-related KLF6 alternative splicing and following P21/CCND1 pathway in osteosarcoma." (PMID 34568030, 2021). "Concomitantly, treatment with DADS downregulates cyclin D1 and c-myc in osteosarcoma 119, and CDK1 and Cyclin B1 in ovarian cancer." (PMID 33390834, 2021). "MiR‐145‐5P inhibits osteosarcoma cell proliferation by targeting inhibit of E2F3b, which affected Cyclin D1, CDK2, CDK4 and CDK6 expression." (PMID 34741389, 2021). "More importantly, we further discovered that KLF6-SV1 attenuated the effect of lnc-KASRT on regulating osteosarcoma cell functions and the P21/CCND1 pathway." (PMID 34568030, 2021). "Results demonstrated that miR-128 knockdown effectively induced osteosarcoma cell apoptosis via decreasing caspase-3 and caspase-9 and arrested Mg63 cells at G2/M phase via inhibition of cyclin D1 and cyclin E2." (PMID 33472642, 2021). "PRI-724 treatment led to decreased protein levels of the Wnt target cyclin D1 in human osteosarcoma cells." (PMID 33923996, 2021). "Specifically, we found that URG4 regulates the cell cycle through the GSK 3β/β-catenin/cyclin D1 pathway, thereby affecting the proliferation of osteosarcoma cells." (PMID 32552851, 2020). "Altogether, GSK 3β/β-catenin/cyclin D1 signaling is involved in URG4-mediated osteosarcoma cell proliferation." (PMID 32552851, 2020). "So we conclude that URG4 can inactivate GSK-3β, thereby activating the β-catenin/cyclin D1 signaling pathway and promoting osteosarcoma cell proliferation." (PMID 32552851, 2020). "A previous study has shown that apatinib treatment can reduce the expression of Cyclin D1 in osteosarcoma cell line KHOS cells and MG63 cells in inhibiting cell cycle." (PMID 32697395, 2020). "By directly binding CCND1 3′-UTR, miR-15a and miR-16-1 inhibited CCND1 transcription, inducing apoptosis and cell cycle arrest in osteosarcoma." (PMID 32190086, 2020). "MALAT1 exerted its oncogenic function in osteosarcoma as a ceRNA to suppress miR-34a expression and upregulate CCND1." (PMID 31143769, 2019). "Cyclin-D1 has been indicated to regulate cell migration/invasion, promote cell proliferation and inhibition of apoptosis in osteosarcoma." (PMID 31238539, 2019). "In support of our results, the loss of TEM8 has previously been linked to reduced proliferation by increasing p21 and p27 levels and by suppressing levels of cyclin D1 in osteosarcoma cell lines." (PMID 30046396, 2018). "Overexpression of miR-195 inhibits cell growth and invasion in osteosarcoma cells by targeting CCND1." (PMID 29113367, 2017). "TRIM14 knockdown suppressed the migration and invasion ability of osteosarcoma cells, and induced downregulation of cyclin D1 and vimentin and simultaneous upregulation of E-cadherin." (PMID 28205534, 2017). "A previous study has indicated that miR-15a and miR-16-1 inhibit apoptosis and cell cycle arrest by downregulating CCND1 in osteosarcoma." (PMID 27813492, 2016). "More importantly, Using real-time PCR, we evaluated the expression of miR-195 and CCND1 in osteosarcoma samples from 107 frozen biopsy tissues and 99 formalin- or paraformalin-fixed, paraffin-embedded (FFPE) tissues." (PMID 25823925, 2015). "In summary, our study suggests miR-195 function as a tumor metastasis suppressor gene by down-regulating CCND1 and can be used as a potential target in the treatment of osteosarcoma." (PMID 25823925, 2015). "Protein expression of WNT1, β-catenin, c-myc, and cyclin D1 in the Wnt pathway was detected by immunohistochemistry (IHC) in an independent group of 46 osteosarcoma samples." (PMID 24942472, 2014). "c-myc protein expression was detected in only 47.8% (22/46) and cyclin D1 protein expression in 52.2% (24/46) of osteosarcoma samples." (PMID 24942472, 2014). "SMO has been identified as a potential drug target in osteosarcoma, as its inhibitor cyclopamine promotes G1 arrests and represses expression of cyclin D1, cyclin E1, SKP2, and pRb." (PMID 23251412, 2012).
osteosarcoma (continued). "In osteosarcoma cells, FOXO1 activation led to decreased CCND1 (encoding cyclin D1) expression." (PMID 37584250, 2023). "Likewise, our findings indicate that the knockdown of EEF1A1 impedes cell proliferation and cyclin D1 expression in osteosarcoma, chondrosarcoma, and antler cartilage cells." (PMID 37446017, 2023). "Then, we found that KLF6-SV1 knockdown inhibited cell proliferation, migration, and invasion, promoted cell apoptosis, and regulated the P21/CCND1 pathway in osteosarcoma, which was in line with previous studies regarding the effect of KLF6-SV1 in other cancers." (PMID 34568030, 2021). "This visual summary shows that lnc-KASRT located on SRSF1, interacts with SRSF1, then regulates alternative splicing of KLF6 to promote KLF6-SV1 coding while inhibiting KLF6-WT coding, and subsequently modifies P21/CCND1 pathway, finally leading to increased growth and invasion of osteosarcoma." (PMID 34568030, 2021). "URG4, which is high-expressed in osteosarcoma, promotes cell cycle progression via GSK3β/β-catenin/cyclin D1 signaling pathway and may be a novel biomarker and potential target for the treatment of osteosarcoma." (PMID 32552851, 2020). "Moreover, URG4 regulates cell cycle and proliferation in osteosarcoma through the GSK3β/β-catenin/cyclin D1 pathway." (PMID 32552851, 2020). "LINC01296 via targeting cyclin D1 could regulate the proliferation, metastasis, and cell cycle of osteosarcoma." (PMID 33330110, 2020). "Tumor progression-associated proteins (VEGF, MMP-9, Cyclin-D1, C-FLIP, MCL-1, and XIAP) may serve as therapeutic targets for inhibition of osteosarcoma progression." (PMID 31238539, 2019). "Our current results also presented that both PD98059 (MEK/ERK pathway inhibitor) and miltefosine (AKT inhibitor) both inhibit the expression of tumor progression-associated proteins (VEGF, MMP-9, Cyclin-D1, C-FLIP, MCL-1, and XIAP) in osteosarcoma U-2 OS cells in vitro." (PMID 31238539, 2019). "In addition, FAM83H-related proliferation and invasiveness of osteosarcoma cells were related to the expression of β-catenin, cyclin D1, p27, snail, and vimentin." (PMID 31215499, 2019). "Cyclin D1 is a key cell-cycle regulator, and its overexpression can shorten the cell cycle and lead to abnormal cell proliferation, inducing a variety of tumors, including osteosarcoma." (PMID 29340064, 2017). "Notably, inhibition of AKT expression by siRNA suppressed cyclin D1 and vimentin levels and increased E-cadherin expression in osteosarcoma cells." (PMID 28205534, 2017). "Of the 50 osteosarcoma cases with elevated miR-195, 30 (60.0%) showed low levels of Cyclin D1." (PMID 25823925, 2015). "However, a study on human osteosarcoma cells shows that the GR represses cyclin D1, the function of which is required for cell cycle G1/S transition, by targeting Tcf-β-catenin, thereby providing evidence for a direct link between GC and Wnt signaling in cell cycle repression by GR." (PMID 37334313, 2023). "FLVCR-AS1 by targeting miR-381-3p/CCND1 could promote osteosarcoma growth." (PMID 33330110, 2020). "Moreover, the expression of Cyclin D1 was positively correlated with the LINC01296 expression in osteosarcoma cells so that LINC01296 knockdown could lead to down regulation of cyclin D1." (PMID 32856843, 2020). "Specifically, further investigation of the potential role of p52 in the regulation of the cell cycle in osteosarcoma cells treated with doxorubicin will be important as others demonstrated p52's ability to influence the expression of several key cell cycle regulators such as Cyclin D1 and p21." (PMID 19746155, 2009).